GLCCI1 (glucocorticoid induced 1)
Diseases named in the same sentence as GLCCI1 in open-access papers (continued):
Sharing a sentence is not in itself a finding about the gene and the disease.
allergic asthma (1 paper, 2024). A asthma with a basis in a pathological type I hypersensitivity reaction. "This study aimed to investigate the role of GLCCI1 in the regulation of nucleotide-binding oligomerization domain (NOD)-like receptor (NLR) family pyrin domain-containing 3 (NLRP3) by the phosphatidylinositol 3-kinase (PI3K) pathway in the pathogenesis of allergic asthma." (PMID 39834584, 2024).
childhood asthma (1 paper, 2020). "Similarly, we found GLCCI1 rs37969, rs37972, and rs37973 polymorphisms were all irrelevant to the risk of childhood asthma in the current study." (PMID 33208131, 2020). "We aimed to determine the associations between stress-induced phosphoprotein 1 (STIP1) and glucocorticoid-induced transcript 1 (GLCCI1) polymorphisms and susceptibility of childhood asthma and inhaled corticosteroid (ICS) response in children." (PMID 33208131, 2020). "And currently, the studies on the two genes (STIP1 and GLCCI1) and Chinese childhood asthma are still rarely reported." (PMID 33208131, 2020).
chronic GVHD (1 paper, 2025). "Multivariate analysis confirmed that GLCCI1 rs37973 AG/AA donors had a significantly reduced risk of chronic GVHD (hazard ratio 0.57, 95% confidence interval 0.35-0.93, P = 0.025)." (PMID 41264074, 2025).
diabetic nephropathy (1 paper, 2024). "Another study reported that the PI3K pathway can regulate the development of diabetic nephropathy by modulating GLCCI1 expression in glomerular podocyte foot processes." (PMID 39834584, 2024).
pneumococcal meningitis (1 paper, 2019). An acute purulent infection of the meninges and subarachnoid space caused by Streptococcus pneumoniae, most prevalent in children and adults over the age of 60. "One study investigated if rs37972 in the glucocorticoid-induced transcript 1 gene (GLCCI1) influenced disease outcome and the response to glucocorticosteroids in pneumococcal meningitis." (PMID 31519222, 2019).
GLCCI1 also shares sentences with these, for which no sentence is quoted: colorectal adenoma (2 papers); rheumatoid arthritis (2); chronic obstructive pulmonary disease (1); glaucoma (1); lymphoblastic leukemia (1); sarcopenia (1); thymoma (1).